IGHV2-26 (immunoglobulin heavy variable 2-26)
Description:
V region of the variable domain of immunoglobulin heavy chains that participates in the antigen recognition. Immunoglobulins, also known as antibodies, are membrane-bound or secreted glycoproteins produced by B lymphocytes. In the recognition phase of humoral immunity, the membrane-bound immunoglobulins serve as receptors which, upon binding of a specific antigen, trigger the clonal expansion and differentiation of B lymphocytes into immunoglobulins-secreting plasma cells. Secreted immunoglobulins mediate the effector phase of humoral immunity, which results in the elimination of bound antigens. The antigen binding site is formed by the variable domain of one heavy chain, together with that of its associated light chain. Thus, each immunoglobulin has two antigen binding sites with remarkable affinity for a particular antigen. The variable domains are assembled by a process called V-(D)-J rearrangement and can then be subjected to somatic hypermutations which, after exposure to antigen and selection, allow affinity maturation for a particular antigen.
Synonyms: IGHV226; VH
Gene: Immunoglobulin variable (V) gene on chromosome 14 (106,301,396 to 106,301,862, reverse strand). Ensembl gene ENSG00000211951.
Subcellular location: Secreted; Cell membrane
Gene Ontology:
Molecular function: antigen binding
Biological process: immunoglobulin mediated immune response
Cellular component: extracellular region; plasma membrane
Homologues: Orthologues: mouse Ighv8-12 (66% identical), mouse Ighv8-6 (66% identical), mouse Ighv8-8 (66% identical), mouse Ighv8-5 (65% identical), mouse Ighv8-9 (64% identical), mouse Ighv8-11 (62% identical), rat AABR07065813.1 (61% identical), mouse Ighv8-13 (58% identical), mouse Ighv8-2 (57% identical), mouse Ighv8-4 (55% identical), rat Igh-6-ps1 (47% identical). Paralogues in human: IGHV2OR16-5 (88% identical), IGHV2-70D (85% identical), IGHV2-70 (84% identical), IGHV2-5 (82% identical), IGHV4-59 (56% identical), IGHV4-61 (56% identical), IGHV4-39 (55% identical), IGHV4-28 (54% identical), IGHV4-4 (53% identical), IGHV4OR15-8 (53% identical), IGHV4-31 (52% identical), IGHV4-34 (51% identical), and 65 more.
Diseases named in the same sentence as IGHV2-26 in open-access papers:
IGHV2-26 is named in the same sentence as 4 diseases in open-access papers, as found by Europe PMC text mining. Sharing a sentence is not in itself a finding about the gene and the disease.
IGHV2-26 shares sentences with these, for which no sentence is quoted: escherichia coli infection (1 paper); staphylococcus aureus infection (1); systemic lupus erythematosus (1); viral myocarditis (1).